ADAM33 (ADAM metallopeptidase domain 33)
Diseases named in the same sentence as ADAM33 in open-access papers (continued):
Sharing a sentence is not in itself a finding about the gene and the disease.
tumor (11 papers, 2009 to 2025). "Lastly, the methylation analysis revealed that ADAM11, ADAM32, and ADAM33 exhibited higher levels of methylation in tumor tissues compared to normal tissues." (PMID 39346916, 2024). "In conclusion, these results proposed ADAM33 gene as a tumor suppressor that can be a beneficial molecular marker of breast invasive lobular cancer." (PMID 38317965, 2024). "Further experiments are warranted to validate the function and relationship of ADAM33 and ADAM33-n and to substantiate the results based on tumor samples and clinical data." (PMID 36977901, 2023). "A statistically significant difference was observed between ADAM33 expression and metastasis (p = 0.049), death (p = 0.024), histological type (p = 0.034) and tumor subclasses (p < 0.001)." (PMID 28294120, 2017). "Another potentially important observation is that in samples showing local tumour recurrence, the ADAM33 promoter methylation frequency was 66.7%, compared to 36.5% for non-recurrent samples (p = 0.201)." (PMID 19267929, 2009). "More studies about ADAM33 protein function in cancer are necessary to understand its tumour-suppressor role." (PMID 19267929, 2009). "The protein encoded by ADAM33 is also a significant metalloproteinase in the ECM, which is crucial for tissue remodeling, and the absence or low expression of this protein contributes to increased tumor aggressiveness and metastasis." (PMID 40446009, 2025). "We also suggest inspecting the mechanisms underlying tumor-suppressing effects of some of the ADAMS such as ADAM-11 and ADAM-33, because despite their genetic basis of actions, their induced molecular pathways that appoint the suppressing effect has not been clear." (PMID 38317965, 2024). "Moreover, ADAM33 expression, death and tumor subclasses (p = 0.021, p < 0.001, p = 0.020, respectively) were considered independent prognostic factors for MFS." (PMID 28294120, 2017). "We evaluated ADAM33 methylation in primary tumour samples by methylation specific PCR (MSP)." (PMID 19267929, 2009). "Unlike the full-length ADAM33, ectopic ADAM33-n inhibits cell growth and colony formation, indicating its tumor suppressor ability." (PMID 36977901, 2023). "It’s believed that ADAM33 may inhibit aggressiveness and metastasis inof TNBC, thus it has the function of tumor suppression." (PMID 34053447, 2021). "Moreover, in DNA methylation alterations of tumor cells induced by GLP-1RAs, studies have demonstrated that during breast cancer progression, tumor suppressor genes such as ESR1, CDH1, and ADAM33 are downregulated due to hypermethylation alterations in their promoter regions." (PMID 40140925, 2025).
cancer (9 papers, 2009 to 2025). A tumor composed of atypical neoplastic, often pleomorphic cells that invade other tissues. "In oncological contexts, ADAM33 expression and differential methylation have been linked to several cancers, including breast, thyroid, and gastric malignancies." (PMID 41373738, 2025). "The ADAM33 gene (coding a transmembrane glycoprotein) is implicated in cancer progression and undergoes changes in cell adhesion." (PMID 38317965, 2024). "Therefore, the relationship between these two entirely different functions of ADAM33 and their underlying mechanisms in cancers remain unclear." (PMID 36977901, 2023). "In contrast, ADAM33 consistently displayed a significant downregulation trend across various cancers." (PMID 39346916, 2024). "Analysis of ADAM33 expression in BC cell lines uncovered gene silencing in 65 % of cancer cell lines." (PMID 38317965, 2024). "ADAM9 was observed to be highly expressed in CHOL, whereas ADAM33 had a significantly lower expression in pan-cancers, especially in BLCA and UCEC." (PMID 37082201, 2023). "Besides, only ADAM33 was negatively related to cancer stemness, still needing further research." (PMID 34368141, 2021). "Although targeting MPs for diseases such as cancer has been historically problematic due to off-target effects, this problem may be overcome by development of specific small-molecule inhibitors of the sADAM33 MP based on the unique ADAM33 crystal structure." (PMID 27489884, 2016). "In addition, we speculate that ADAM33 is involved with the KIT oncogene pathway in cancer, given that the ADAM33 catalytic domain is capable of cleaving SCF (Kit ligand) in vitro." (PMID 19267929, 2009). "To comprehensively understand these four lncRNAs (LINC01224, CASC9, LINC00346, and TRPM2-AS) and seven target mRNAs (CCNF, PKMYT1, GCH1, TK1, PSAT1, ADAM33, and DDX11), we performed genome instability, immune, cancer stemness, and drug sensitivity analysis." (PMID 34368141, 2021).
cardiovascular disease (2 papers, 2013 to 2018). "Moreover, recently ADAM33 was linked to cardiovascular disease (CVD), emphasizing its potential pleiotropic role in age-related diseases." (PMID 23861802, 2013). "Given the physiological importance of ADAM33 in pulmonary and cardiovascular diseases, we hypothesize that ADAM33 has an impact on mortality due to these disorders." (PMID 23861802, 2013). "So far the role of ADAM33 in cardiovascular disease is poorly understood." (PMID 23861802, 2013). "Overproduction of ADAM33 may lead to excessive shedding of inflammatory mediators and growth factors, which induce pathological states like proliferation of smooth muscle cells and fibroblasts observed in pulmonary and cardiovascular disorders." (PMID 23861802, 2013). "In summary, this study implicates that ADAM33 is involved in all-cause mortality and in mortality due to both COPD and cardiovascular disease and these associations are independent of level of lung function, gender and smoking habits." (PMID 23861802, 2013).
infection (2 papers, 2020 to 2023). The state of being infected such as from the introduction of a foreign agent such as serum, vaccine, antigenic substance or organism. "In addition, children with acute infectious pneumonia of viral etiology showed an increased protein expression of ADAM28 and ADAM33 in the lung, which was correlated with the severity of infection and is likely to be involved in the chronicity and fibrosis development." (PMID 33392273, 2020). "ADAM10 and ADAM17 together with ADAM8 and ADAM9 seem to be the most relevant ADAM proteases in infection; however, some studies point toward an additional influence of ADAM12, ADAM15, and ADAM33." (PMID 33392273, 2020).
inflammation (1 paper, 2006). Aberrant reaction of the microcirculation characterized by movement of fluid and leukocytes from the blood into extravascular tissues. "ADAM33 and its so far identified polymorphisms may have less to do with atopic inflammation and more with non atopic lung specific forms of asthma." (PMID 16784537, 2006).
respiratory diseases (1 paper, 2014). "S1 and S2 were associated with COPD in this population, reflecting the potential role of ADAM33 in airway remodeling in multiple respiratory diseases." (PMID 25369941, 2014).
ADAM33 also shares sentences with these, for which no sentence is quoted: atopic dermatitis (3 papers); Airway obstruction (2); atopic asthma (2); cutaneous disorders (2); sarcoidosis (2); breast (1); chronic lung disease (1); colon cancer (1); conjunctivitis (1); coronary heart disease (1); cystic fibrosis (1); dermatitis (1); diabetes mellitus (1); diarrheal disease (1); Hyperinsulinemia (1); hyperreactivity (1); immune system diseases (1); Insulin resistance (1); ischemic stroke (1); kidney disease (1); laryngeal carcinoma (1); lung carcinoma (1); pulmonary fibrosis (1); respiratory infection (1); sarcoma (1); triple-negative breast carcinoma (1); type 1 diabetes (1); type 2 diabetes (1).